RMND5B (required for meiotic nuclear division 5 homolog B)
Description:
Core component of the CTLH E3 ubiquitin-protein ligase complex that selectively accepts ubiquitin from UBE2H and mediates ubiquitination and subsequent proteasomal degradation of the transcription factor HBP1. MAEA and RMND5A are both required for catalytic activity of the CTLH E3 ubiquitin-protein ligase complex. Catalytic activity of the complex is required for normal cell proliferation. The CTLH E3 ubiquitin-protein ligase complex is not required for the degradation of enzymes involved in gluconeogenesis, such as FBP1.
Synonyms: FLJ22318; GID2; GID2B
Tractability: PROTAC: ubiquitination databases record sites on it.
Gene: Protein-coding gene on chromosome 5 (178,129,068 to 178,152,240, forward strand). Ensembl gene ENSG00000145916.
Subcellular location: Cytoplasm, cytosol
Pathways (Reactome):
Metabolism: Regulation of pyruvate metabolism
Gene Ontology:
Molecular function: protein binding; ubiquitin protein ligase activity; ubiquitin-protein transferase activity
Biological process: proteasome-mediated ubiquitin-dependent protein catabolic process
Cellular component: cytosol; GID complex; nucleus; cytoplasm
Genetic constraint (gnomAD): Loss-of-function variants: 40 observed, 51 expected, observed/expected ratio (o/e) 0.78, 90% interval 0.61 to 1.02. The upper end of that interval is the gene's LOEUF score, 1.02, which puts it in group 4 of 6, group 1 being the genes least tolerant of losing a copy. Missense variants: 461 observed, 530.13 expected, observed/expected ratio (o/e) 0.87, 90% interval 0.81 to 0.94. Synonymous variants: 220 observed, 220.46 expected, observed/expected ratio (o/e) 1, 90% interval 0.89 to 1.12.
Homologues: Orthologues: chimpanzee RMND5B (99% identical), macaque RMND5B (98% identical), rat Rmnd5b (98% identical), mouse Rmnd5b (98% identical), guinea pig RMND5B (96% identical), dog RMND5B (93% identical), pig RMND5B (88% identical), zebrafish rmnd5b (73% identical), Drosophila melanogaster Sou (44% identical), Caenorhabditis elegans gid-2 (26% identical). Paralogues in human: RMND5A (70% identical), MAEA (24% identical).
Diseases named in the same sentence as RMND5B in open-access papers:
RMND5B is named in the same sentence as 4 diseases in open-access papers, as found by Europe PMC text mining. Sharing a sentence is not in itself a finding about the gene and the disease. The quoted sentences say what the papers report.
pancreatic cancer (1 paper, 2023). "In this study, RMND5B was found to be low risk in the risk model, and Cell RT-qPCR validation revealed that its levels were suppressed in multiple pancreatic cancer cells, implying that it may exist as a tumor suppressor gene in pancreatic cancer, which contradicts the findings from other studies." (PMID 37396042, 2023).
prostate carcinoma (1 paper, 2023). A carcinoma that arises from epithelial cells of the prostate gland. "Overexpressed RMND5B has been shown to inhibit NKX3.1 factor in prostate cancer to suppress its ubiquitination and nuclear levels so as to promote tumor proliferation." (PMID 37396042, 2023).
tumor (2 papers, 2023 to 2024). "The carboxy terminus of LisH (CTLH) complex representing RMND5B can promote tumor maintenance and rapid proliferation under extreme conditions and is associated with EMT and, wnt/β-catenin pathway." (PMID 37396042, 2023). "However, this experiment indicates that RMND5B is actually under-expressed in tumor tissues, suggesting that the activity of this gene may be enhanced in a number of ways (gene, mutations, chromosomal rearrangements, gene amplification, etc.), not necessarily by overexpression." (PMID 38903709, 2024). "The RT-qPCR result revealed that ALOX12 was markedly up-regulated (P=0.0144) and RMND5B was markedly down-regulated (P=0.0016) in tumor samples compared with controls, while the expression of CTSC was not notably different (P=0.7259) between tumor and control samples." (PMID 38903709, 2024).
cancer (1 paper, 2023). A tumor composed of atypical neoplastic, often pleomorphic cells that invade other tissues. "RMND5B has E3 ligase activities and its overexpression in tumors is critical for cancer cell therapy resistance." (PMID 37396042, 2023).